TMPRSS2 (transmembrane serine protease 2)
Diseases named in the same sentence as TMPRSS2 in open-access papers (continued):
Sharing a sentence is not in itself a finding about the gene and the disease.
viral infection (continued). "During virus infection, many coronaviruses, including SARS-CoV-1, SARS-CoV-2, Middle East respiratory syndrome coronavirus (MERS-CoV), and human coronavirus 229E (HCoV-229E), as well as influenza viruses, use the host protease TMPRSS2 as a tool to enter the human cells." (PMID 41408854, 2025). "Further, NHP plasma capability to inhibit the viral infection to the cells was tested in vitro using an early circulating strain of SARS-CoV-2 viruses and VeroE6 constitutively expressing transmembrane protease, serine 2 (TMPRSS2) for facilitating the infection." (PMID 38569556, 2024). "Since viral infections have a strong influence on the transcriptional changes within infected cells, we wanted to investigate whether SARS-CoV-2 infection could influence the level of expression of ACE2 and TMPRSS2 mRNAs in the respiratory tract." (PMID 38230954, 2024). "Some papers propose that this may be due to a different expression of angiotensin-converting enzyme 2 (ACE-2) or transmembrane protease serine 2 (TMPRSS2) receptors, or to lower production of proinflammatory cytokines such as interleukin-6 (IL-6) in women after a viral infection." (PMID 39036098, 2024). "According to a recent study, the endolysosome proteases TMPRSS-2 and cathepsins B and L activate the SARS-CoV-2 S protein in an acidic environment, which is why the deacidification of this organelle has been found to inactivate proteases and prevent viral infection." (PMID 36899912, 2023). "Proteins such as transmembrane serine protease 2 (TMPRSS2), endoprotease (Furin) and cathepsin L (CTSL) activate the S protein of SARS-CoV-2 to facilitate the fusion of SARS-CoV-2 and IECs membranes, thereby enhancing virus infection and leading to GI symptoms." (PMID 38156008, 2023). "Secondly, we found that ACE2 and TMPRSS2 expression in the liver was significantly higher in NAFLD patients who experienced SARS-Cov-2 infection (n = 6) compared to those who had not undergone viral infection (n = 9)." (PMID 36366497, 2022). "Another limitation is that in our system viral infection occurs in a non-clinical cell system, and therefore does not exhibit dependency in TMPRSS2, which has been shown to be required for viral cell entry on the surface of the target cell and for fusion between viral and cell membranes." (PMID 35458533, 2022). "In the light of our findings where TRIM31 is positively correlated with TMPRSS2-TMPRSS4 in GI tumors and knockdown of TRIM31 mediates viral replication and viral processes, developing inhibitors targeting TRIM31 may decrease viral infection efficiency of SARS-CoV-2 in colorectal cancer patients." (PMID 35970857, 2022). "A significant elevation of Furin expression was observed in the lungs of infected hamsters regardless of age (2.3-fold in young and 2.9-fold in aged hamsters, p < 0.0001, two-way ANOVA), although expression of Tmprss2 was not significantly altered following virus infection." (PMID 34834944, 2021). "Sfull virus infection, as measured by N antigen-positive cells, was sensitive to inhibition by E-64d but not camostat in Vero cells, suggesting that Sfull virus enters the TMPRSS2-negative Vero cells through the endosomal pathway." (PMID 33574281, 2021). "We implemented this assay in a high‐content, 384‐well microplate format using HEK293T cells, which are not susceptible to viral infection unless transfected with ACE2 and TMPRSS2, and Calu‐3 lung cancer cells, which possess the replete machinery for spike‐mediated viral infection." (PMID 34339582, 2021). "Expression of ACE2 alone may not be sufficient for viral infection, and other factors, such as transmembrane protease serine 2 (TMPRSS2), cathepsin, and other proteases and binding proteins may be essential." (PMID 34151246, 2021).
viral infection (continued). "The expression of TMPRSS2 seems to be higher compared to that of ACE2 and occurs in both neurons and non-neuronal cells in the olfactory epithelium and with a mosaic pattern, suggesting that some olfactory neurons may be more vulnerable to viral infection." (PMID 32580925, 2020). "Moreover, our data regarding viral entry and processing genes suggests that any viral infection in endothelial cells may occur via different routes to nasal epithelium, which is thought to use ACE2 and TMPRSS2, at 2 key levels." (PMID 33073064, 2020). "During viral infection, the spike protein is cleaved into these S1 and S2 subunits by nearby host proteases, such as human airway trypsin-like protease (HAT), cathepsins and transmembrane protease serine 2 (TMPRSS2), and releases the signal peptide to promote virus entry into host cells." (PMID 32927621, 2020). "Therefore, ACE2, TMPRSS2, and CLEC4M could support viral infection through the space of Disse." (PMID 38074511, 2024). "Similarly, in the ACE2/TMPRSS2-reconstituted lung epithelial cell line A549, expression of subgenomic nucleocapsid RNA and innate immune gene expression were indistinguishable for both virus infections." (PMID 36383605, 2022). "We further demonstrated that FBP could not significantly inhibit SARS-CoV-2 replication in Calu-3 cells, in which SARS-CoV-2 relied on TMPRSS2 but not on endocytosis for viral infection, which was consistent with the activity of FBP against SARS-CoV-2 by inhibiting endosomal acidification." (PMID 35259078, 2022). "Moreover, our findings demonstrate that TRIM31 is positively correlated with TMPRSS2-TMPRSS4 genes in GI samples suggesting a possibility of TRIM31 acting alongside with TMPRSS2-TMPRSS4 protease pair in SARS-CoV-2 viral entry and promoting viral infection in GI cells." (PMID 35970857, 2022). "Our molecular and biochemical experiment identified a new role of TMPRSS2, independent of its known protease activity, during SARS-CoV-2 and YFV viral infection." (PMID 38185627, 2024). "Unlike pre-treatment with furin, TMPRSS2, or trypsin, all of which increased VSV-SARS-CoV-2 infection at low doses, pre-treatment with FXa reduced viral infection regardless of the dose." (PMID 37024459, 2023). "Overall, while inhibition of either entry route effectively inhibits viral infection, inhibition of endosomal acidification via V-ATPase inhibition alone is effective at neutralizing SARS-CoV-2 entry irrespective of TMPRSS2 expression." (PMID 35703551, 2022). "Therefore, it is important to understand these non-canonical SARS-CoV-2 entry-mediating proteins (i.e., other than ACE2 and TMPRSS2) so that we can establish effective methods to block viral replication in those tissues in which ACE2/TMPRSS are poorly expressed or not employed for viral infection." (PMID 35517495, 2022). "However, in our study, we could not see such an effect of TMPRSS2 on viral infection." (PMID 34805783, 2021). "Treatment with camostat has no impact on Sfull virus infection in A549-ACE2 cells, as no or minimal TMPRSS2 is expressed, suggesting that other TMPRSS2 homologs or trypsin-like proteases may activate the Sfull virus entry at the plasma membrane." (PMID 33574281, 2021).
prostate tumors (71 papers, 2008 to 2025). "By interrogating 2604 different prostate tumors from eight cBIOPortal studies, genes harboring the 25 truncal mutations and the TMPRSS2-ERG fusion were found altered." (PMID 32313004, 2020). "The most frequently rearranged member of this family is the Ets Related Gene (ERG), which is overexpressed through gene fusion with the 5′ untranslated region of the gene encoding Transmembrane protease, serine 2 (TMPRSS2) in ∼40% of prostate tumors." (PMID 27626314, 2016). "Collectively, these results establish that TRIM25 is an ubiquitin ligase of full-length ERG as well as the N-terminally truncated ERG variants that originate from the TMPRSS2-ERG gene fusion in prostate tumors." (PMID 27626314, 2016). "NBC correctly identifies a known fusion gene (TMPRSS2-ERG) in aCGH data from 36 prostate tumors and predicts gene truncations, structural variants, and fusion genes in aCGH data from glioblastoma." (PMID 21510904, 2011). "Studies have reported a higher frequency of PTEN loss and TMPRSS2:ERG fusion in prostate tumours of Black/African American men, which may contribute to the more aggressive nature of the disease in this population." (PMID 40165885, 2025). "Several AR-associated genes (AR, FOLH1, KLK3, NKX3-1, TMPRSS2) showed minimal change in the metastatic dura adenocarcinoma as compared to the primary prostate tumor, while there was a marked downregulation of these AR-related transcripts in the metastatic brain NEPC lesion." (PMID 39349591, 2024). "TMPRSS2–ERG fusion in prostate tumors could be implicated in the activation of NOTCH pathway, capable of increasing proliferation and maintenance of progenitor cells." (PMID 34399734, 2021). "Overall, studies presented here show that the interaction between Type I and Type II splice variants of TMPRSS2-ERG present in prostate tumor tissues may lead to functional antagonism of selected variants." (PMID 25221645, 2014). "In contrast, other gene loci that are highly expressed in prostate tumor cells, such as TMPRSS2 and KLK3 showed very different (and expected) methylation patterns in the same dataset, excluding the possibility of an artifact in the WGBS." (PMID 38112617, 2024). "Dysregulated TMPRSS2 activity is related to the proliferation, invasiveness, and metastasis of prostate tumor cells." (PMID 38438396, 2024). "Because the expression of ERG in prostate tumor tissue is primarily driven by the TMPRSS2–ERG fusion event, we inferred the ERG fusion status based on the expression level of the ERG gene." (PMID 39347576, 2024). "We further quantified global gene expression changes, which revealed differential expression of genes related to microtubules, immune function, and TMPRSS2-fusion pathways, specifically in prostate tumors of AA men." (PMID 38566104, 2024). "In fact, gene rearrangement is observed in the majority (57–80%) of PCa tissue samples, and the TMPRSS2/ERG rearrangement in particular is present in 50% of prostate tumors." (PMID 38674385, 2024). "TMPRSS2::ERG was only identified by FusionInspector in prostate tumors or normal prostate, reflecting both this fusion’s high tissue specificity and FusionInspector’s high specificity of fusion calling." (PMID 37323575, 2023). "Each of the five TCGA prostate normal samples containing TMPRSS2::ERG were found with TMPRSS2::ERG in their matching prostate tumor samples, likely due to tumor-in-normal contamination." (PMID 37323575, 2023). "The most frequent gene rearrangements found in primary prostate tumors are those involving TMPRSS2 (Transmembrane Serine Protease 2) and members of the ETS (erythroblast transformation specific transcription factor) family transcription factors." (PMID 36937425, 2023). "The ETS transcription factor ERG is aberrantly expressed in approximately 50% of prostate tumors due to chromosomal rearrangements such as TMPRSS2/ERG." (PMID 37956771, 2023).
prostate tumors (continued). "The TMPRSS2/ERG gene rearrangement found in prostate tumors results in ERG expression in prostate cells, a cell type where ERG is not normally expressed." (PMID 33554122, 2021). "The TMPRSS2/ERG gene rearrangement occurs in 50% of prostate tumors and results in expression of the transcription factor ERG, which is normally silent in prostate cells." (PMID 34314419, 2021). "Along with this, it is attractive to observe that the TMPRSS2:ERG fusion gene is found in approximately 50% of prostate tumours of whites whereas is infrequent in black and Asian men." (PMID 32774170, 2020). "Renal cancer expressed higher percent positivity of all receptors except TMPRSS2, which exhibited the highest percent positivity in prostate tumor tissues." (PMID 33330620, 2020). "Assume true fusion occurs in less than 2% of samples, as TMPRSS2-ERG achieves the highest occurrence to date at 0.953% of all TCGA tumor samples (14.657% occurrence rate in prostate tumor samples)." (PMID 30340508, 2018). "Further advances in gene expression profiling and bioinformatics have revealed the overexpression of ERG in prostate tumors that led to the discovery of TMPRSS2-ERG fusion." (PMID 29690565, 2018). "An early and common event in prostate tumour development involves a translocation that forms a TMPRSS2:ERG fusion, bringing the ERG transcription factor under transcriptional control of the more active TMPRSS2 promoter." (PMID 29892050, 2018). "As the highest recurrent chimeric transcript, the group harboring TMPRSS2-ERG transcripts shows the highest iFCRaverage values among primary prostate tumor groups." (PMID 29181411, 2017). "In contrast, only two TMPRSS2-ERG-positive prostate tumors were detected in 12 KANSARL-negative prostate tumors." (PMID 28881586, 2017). "More studies are required to determine the prognostic value of ERG in different ethnic groups, particularly in African American and Asian patients with prostate tumors harboring less TMPRSS2/ERG fusion." (PMID 27191272, 2016). "Deregulated expression of a set of ABC genes was particularly evident in the TMPRSS2-ERG-negative prostate tumors." (PMID 26459268, 2015). "Based on these findings, we then used VCaP cells which express both TMPRSS2-ERG variants, allowing us to carry out studies mimicking the in vivo context of prostate tumors." (PMID 25221645, 2014). "Along these lines, our laboratory cloned and sequenced the relatively abundant full length TMPRSS2-ERG cDNAs from a pool of mRNAs from six TMPRSS2-ERG positive prostate tumors." (PMID 25221645, 2014). "For example, cysteine-rich secretory protein 3 (CRISP3) gene expression was found to be associated with the ERG condition, since it was overexpressed in TMPRSS2-ERG fusion-positive prostate tumors as compared to normal tissue." (PMID 24739220, 2014). "PTEN deletion and the TMPRSS2:ERG rearrangement are the two most common genomic aberrations in prostate tumors." (PMID 24642271, 2014). "Towards the bioinformatic analysis of TMPRSS2-ERG regulatory elements we mapped the transcription start sites (TSS) of TMPRSS2 gene in TMPRSS2-ERG fusion harboring human prostate tumors." (PMID 24418414, 2014). "We apply NBC to aCGH data from 36 primary prostate tumors and identify 12 novel rearrangements, one of which is the well-known TMPRSS2-ERG fusion gene." (PMID 21510904, 2011). "We apply NBC to aCGH data from 36 primary prostate tumors and predict 12 CNVs, including one gene truncation and one fusion gene which is the well-known TMPRSS2-ERG fusion gene." (PMID 21510904, 2011). "Although TMPRSS2–ERG fusion has typically been reported as prevalent in 40–50% of prostate tumours, the range has varied by as much as 25–60%." (PMID 20068566, 2010).
prostate tumors (continued). "The identification of TMPRSS2 translocations in about 50% of prostate tumors underscores the significance of structural rearrangements in solid tumors." (PMID 18364049, 2008). "Of the 372 unique prostate tumors, 214 (57.4%) were scored for the TMPRSS2-ERG fusion, one tumor (0.3%) was equivocal and 157 (42.4%) tumors were not scored due to technical issues (core drop-off or failed hybridization)." (PMID 18694509, 2008). "However, TMPRSS2-ERG transgenic mice do develop aggressive prostate tumors at advanced age (>2 years), highlighting a context-dependent action of TMPRSS2-ERG in PCa pathogenesis." (PMID 37537199, 2023). "Notably, genes associated with luminal differentiation (i.e. FOXA1, TMPRSS2, HOXB13, KLK3, KLK2) had significantly reduced expression in the ‘low’ NKX3.1 prostate tumors." (PMID 30266798, 2018). "Furthermore, additional analyses performed by Ren and colleagues on 54 prostate tumor samples confirmed the presence of TMPRSS2-ERG fusion in Chinese population at lower frequency (about 20%) with respect to that observed in Caucasian patients." (PMID 28114882, 2017). "From a carefully characterized RNA pool of ERG expressing and TMPRSS2-ERG fusion harboring prostate tumors obtained from six radical prostatectomy specimens, cDNA molecules were generated and amplified using 5’ cap-specific forward primers and ERG-specific reverse primers." (PMID 24418414, 2014). "More recent studies have identified that a majority of prostate tumors harbor prostate-specific TMPRSS2 gene and the ERG oncogene (TMPRSS2: ERG) gene fusion which could be used as a stem cell marker with high specificity providing ERG-driven survival advantages." (PMID 35800367, 2022). "Relatively few recurrent point mutations are identified in primary prostate tumors; however, approximately 50% of prostate tumors carry a TMPRSS2-ERG translocation, which could be considered a highly tumor-specific molecular biomarker for ctDNA quantification in blood or urine samples." (PMID 31915468, 2019). "To further analyze how 5hmC marks different mechanisms of gene activation, we studied the activating TMPRSS2-ERG fusion (T2E), a somatic alteration present in ∼50% of prostate tumors." (PMID 36251389, 2022). "Fusion proteins involving TMPRSS2, particularly those involving ERG and other ETS family members, are common SV alterations in prostate tumors." (PMID 35715489, 2022). "In human CaP, gene fusion between androgen responsive regulatory elements at the 5'-untranslated region of TMPRSS2 and ETS-related genes (ERG) is present in at least 50% of prostate tumors." (PMID 31303963, 2019). "Recent discoveries that highlight the higher frequencies of TMPRSS2-ERG gene fusion and PTEN deletion in prostate tumors of CA men compared to AA men increasingly support the idea that CaP of AA and CA men have distinct somatic gene alterations." (PMID 29690565, 2018). "The fusion of TMPRSS2-ERG leads to over-expression of ERG in the prostate gland; this promotes prostate tumour initiation and progression." (PMID 25933120, 2015). "Separate clonality analyses of both TMPRSS2-ERG REARRs and of the accompanying 3 Mb interstitial deletion in two prostate tumors (P03-2345 and PR-09-146) demonstrated perfect agreement." (PMID 25160065, 2014). "For example, some indications have emerged that prostate tumors with high levels of vitamin D (1,25-dihydroxyvitamin D3) receptors (VDR) are twice as likely to be TMPRSS2-ERG fusion-positive than those with the low VDR levels." (PMID 24739220, 2014). "A rearrangement of chromosome 21 that results in fusion of the TMPRSS2 and ERG genes occurs in approximately 50% of prostate tumors." (PMID 24642271, 2014). "The most common fusion involves androgen-regulated TMPRSS2 gene with an oncogenic ETS family transcription factor ERG gene, which is reported in 50% of surgical prostate tumors." (PMID 24133629, 2013).